SOX12 (SRY-box transcription factor 12)
Diseases named in the same sentence as SOX12 in open-access papers (continued):
Sharing a sentence is not in itself a finding about the gene and the disease.
cancer (21 papers, 2014 to 2025). A tumor composed of atypical neoplastic, often pleomorphic cells that invade other tissues. "Accumulating evidence suggests that mutations, deletions or overexpression of the SOX12 gene are closely related to the initiation and development of various types of malignant tumors." (PMID 40593465, 2025). "The increased expression of SOX12 has been reported to be associated with malignant transformation and metastasis in several cancer types, including colorectal, lung, liver, gastric, and breast cancers." (PMID 40593465, 2025). "SOX12, as a cancer stem cell marker, is highly expressed in CRC; besides, overexpression of SOX12 facilitates the proliferation and migration of CRC cells." (PMID 40592832, 2025). "Overall, these data suggest that the regulation of SOX12 expression in several types of cancers is significantly related to patient survival." (PMID 34442467, 2021). "SOX12 has been demonstrated to exhibit a regulatory function in carcinogenesis and cancer progression." (PMID 34868396, 2021). "The analysis of SOX4, SOX11, and SOX12 expression revealed that their expression was correlated with patient survival in several types of cancers." (PMID 34442467, 2021). "The expression of genes related to SOX4, SOX11, and SOX12, which are highly upregulated in various types of cancers, and their related signaling pathways were also examined using a gene meta-analysis database." (PMID 34442467, 2021). "Expression and phylogenetic tree analyses of the SOX gene family revealed that the expression of three closely related SOX members, SOX4, SOX11, and SOX12, was increased in multiple cancers." (PMID 34442467, 2021). "In the present study, we revealed that phylogenetically close SOX members, SOX4, SOX11, and SOX12, have distinctively higher expression in various cancers, and analyzed the prognostic value and correlated pathways using various bioinformatic tools." (PMID 34442467, 2021). "Among the genes in the SOX family, the expression of SOX4, SOX9, SOX11, and SOX12 was higher in multiple types of cancers than in their normal counterparts." (PMID 34442467, 2021). "SOX12 has been characterized as an oncogene in various cancers to promote multiple malignant processes, including cell proliferation, survival, migration, and invasion." (PMID 30858360, 2019). "SOX12 is a key cancer‐related protein in many human cancers." (PMID 41425852, 2025). "SOX12 acted as a cancer stem-like cell marker and could promote malignant phenotypes of HCC, such as metastasis." (PMID 35465267, 2022). "Furthermore, some cancer-related microRNAs (miR), such as miR-874 and miR-744, have been reported to directly target SOX12 and suppress its action." (PMID 39132059, 2022). "What is more, LINC00978 knockdown could repress HCC cellular growth and cancer metastasis through mediating microRNA −125b-5p/SOX12 axis." (PMID 35485164, 2022). "SOX12’s promotion function has been reported in several cancers, including OC." (PMID 34789303, 2021). "SOX12 has been actively studied in recent years and is known to affect cancer characteristics." (PMID 34442467, 2021). "Furthermore, the relative mRNA expression levels of other SOX family members, such as SOX11 and SOX12, are elevated in breast, liver, and lung cancers and have a positive correlation with poor prognosis." (PMID 34442467, 2021). "Furthermore, Kaplan–Meier analysis based on TCGA datasets revealed that patients with high levels of SOX12 had shorter OS than patients with low levels of SOX12, strongly suggesting that SOX12 contributes to the progression of these human cancers." (PMID 30858360, 2019). "Therefore, our analysis may contribute valuable insights into SOX4, SOX11, and SOX12 as a potential therapeutic goal for various human cancers." (PMID 34442467, 2021). "Future research should focus on further elucidating the precise mechanisms by which SOX12 and YBX1 regulate LDHA and exploring the potential of the targeting of this axis in other cancer types." (PMID 40593465, 2025).
cancer (continued). "Although SOX12 has the weakest transactivation domain among the SOXC proteins it was shown to play a role in the inflammatory response of T cells and cancer cells." (PMID 35529852, 2022). "High expression of CERCAM, HS6ST2, ONECUT2, SOX12 and TMEM132A and low expression of MIA2 related to poor outcomes for progression-free survival and cancer-specific survival." (PMID 35954418, 2022). "Phylogenetic tree analysis showed that the highly expressed SOX members in various cancers, i.e., SOX4, SOX11, and SOX12, were closely clustered, suggesting similarities in amino acid sequences among these three SOX members." (PMID 34442467, 2021). "Among these target genes, KLK9, WNT3A, FGF18, FIBP, SOX12, TGFBI, and NEDD9 have been reported to participate in the development of human cancers." (PMID 33344223, 2020). "In addition, it was found that the repressed effect by LINC00978 depletion on cellular growth and cancer metastasis in HCC was rescued by inhibiting microRNA −125b-5p and overexpressing SOX12." (PMID 35485164, 2022). "Although this study demonstrates that miR-127 also downregulates other genes that are overexpressed in cancer, such as FOXO6, SOX11, SOX12, and FASN, it provides the first example that targeting NANOS1 could be a potential cancer treatment strategy." (PMID 36012673, 2022). "Even though SOX12 was not related to miR‐296‐5p and HMGA1 was positively correlated with miR‐296‐5p, their interactions were reported in other cancers." (PMID 39995883, 2025). "Although it has been reported previously that higher expression of SOX4, SOX11, and SOX12 is negatively correlated with patient survival in various cancers, the expression of SOXC members has not yet been analyzed systematically in multiple cancer datasets." (PMID 34442467, 2021). "In addition, the mRNA expression of SOX12 was significantly upregulated in BRCA, ESCA, LUSC, and LUAD regardless of the cancer stage compared to their normal tissues." (PMID 34442467, 2021). "Our analysis also identified deregulated SOX genes such as SOX12 and SOX30, which have not been well characterized in the context of cancer, suggesting these genes may be worthwhile candidates for further investigation." (PMID 25594027, 2014).
neurodevelopmental disorder (1 paper, 2024). A behavioral and cognitive disorder with onset during the developmental period that involves impaired or aberrant development of intellectual, motor, or social functions. "This study addresses a critical gap in the existing literature by investigating the role of SOX12 in neurodevelopmental disorders." (PMID 39057025, 2024). "As previously documented, this gene is predominantly expressed in brain tissues, and notably, except for SOX12, all the members of the C group have an entry code assigned to neurodevelopmental disorders." (PMID 39057025, 2024).
SOX12 also shares sentences with these, for which no sentence is quoted: adenoma (1 paper); Clear Cell Renal Cell Carcinoma (1); Coffin–Siris syndrome 10 (1); Coffin–Siris syndrome 9 (1); esophageal cancer (1); glaucoma (1); hematological malignancies (1); hypogonadotropic hypogonadism (1); melanoma (1); microcephaly (1); pancreatic ductal adenocarcinoma (1); renal carcinoma (1); renal cell carcinoma (1); sarcoma (1); speech delay (1); squamous cell carcinoma of the esophagus (1).